METTL3 (methyltransferase 3, N6-adenosine-methyltransferase complex catalytic subunit)
Diseases named in the same sentence as METTL3 in open-access papers (continued):
Sharing a sentence is not in itself a finding about the gene and the disease.
tumor (continued). "Further studies showed that circMETTL3 could act as a sponge for miR-34c-3p and promote cell proliferation, invasion, tumor growth and metastasis by up-regulating the expression of miR-34c-3p target gene METTL3." (PMID 35004298, 2021). "miRNA, which was regarded as specific transcription factors of METTL3, could decrease the expression and function of METTL3, thereby reversing the tumor-promoting effect of METTL3." (PMID 33879256, 2021). "However, METTL3 also impairs CD8+ T cells tumor killing ability through sustaining the suppression roles of regulatory T cells (Tregs)." (PMID 34526985, 2021). "ALKBH5 was found to have the opposite function to METTL3, it could serve as a tumor suppressor gene in CRC by reducing the nuclear accumulation of RP11 and thus inhibiting the function of EMT." (PMID 33836813, 2021). "In summary, our data demonstrate the critical role of Mettl3 in driving BCa progression, as featured by expediting angiogenesis surrounding tumor cells, and unveil a previously unrecognized signaling axis involving Mettl3-TEK-VEGF-A-CD31/CD34 in bladder malignancy." (PMID 33681207, 2021). "Chemoresistance induced by METTL3 were detected in several kinds of cancers, indicating that functional inhibition of METTL3 might restore the chemosensitivity of tumor cells." (PMID 33879256, 2021). "This interesting result showed that METTL3 could be a tumor suppressor when its knockout could enhance sorafenib resistance, promote angiogenesis-associated genes expression, and activate pathway-associated autophagy in HCC cells under hypoxia condition." (PMID 34745970, 2021). "Overexpression of METTL3 could significantly reduce the inhibitory effect of metformin in tumor growth." (PMID 33431790, 2021). "In tumor tissues resected from liver cancer patients, increased expression of Snail and malignant behaviors were observed, in line with elevated expression of METTL3 and YTHDF1." (PMID 34046411, 2021). "The increased METTL3 protein levels in tumor tissue were detected by Western blotting." (PMID 35117988, 2021). "Our study collectively reported a novel epigenetic mechanism and compelling evidence that METTL3 may enhance the translational efficiency and tumor suppressor function of FBXW7 via a multi-step process involving mRNA m6A methylation." (PMID 33676554, 2021). "The finding that Mettl3 deletion in NK cells induced accelerated tumor growth prompted investigation of whether METTL3 was required for NK cell maintenance." (PMID 34535671, 2021). "METTL3 knockdown in NSCLC inhibits tumor growth, metastasis and DDP resistance." (PMID 33390849, 2021). "However, the role of Mettl3 in BCa progression and tumor microenvironment regulation in vivo remains elusive." (PMID 33681207, 2021). "However, what stimulates METTL3 overexpression in OC is still unclear, and there is a lack of experimental data inferring the interaction mode between METTL3 and the tumour microenvironment." (PMID 34895230, 2021). "Importantly, knockdown of METTL3 in ccRCC cell line impaired both cell migration capacity and tumor spheroid formation in soft fibrin gel, a mechanical method for selecting stem-cell-like tumorigenic cells." (PMID 34631715, 2021). "Moreover, we observed that USP4 knockdown effectively alleviated METTL3 knockdown-induced inhibited xenograft tumor growth." (PMID 34335955, 2021). "In other tumours, METTL3 and METTL14 play an tumour suppressive role." (PMID 33461542, 2021). "METTL3 also promotes tumour formation in nude mice by downregulating the expression of SMG1." (PMID 34246319, 2021). "Increased tumor proliferation and cell cycle progression occurred as a result of METTL3 inhibition." (PMID 34178650, 2021). "Notably, several specific m6A regulators play dual roles in cold tumor formation, such as METTL3, METTL14, and YTHDF1, suggesting the exact role m6A RNA modification-mediated cold tumor formation is tumor-type dependent." (PMID 34616742, 2021).
tumor (continued). "Furthermore, in a xenograft model, silencing METTL3 slowed tumour growth, whereas blockade of phosphatase and tensin homolog (PTEN) counteracted the anticancer effects of shMETTL3." (PMID 34895230, 2021). "Inhibition of METTL3 also decreased tumor cell proliferation by means of CCK8 assay." (PMID 34729106, 2021). "METTL3 could play different roles in the EMT of different tumour cells, and we observed an inhibitory effect of METTL3 on the EMT of ARPE‐19 cells." (PMID 33759344, 2021). "This study identified a tumor suppressor of METTL3 in sorafenib resistance." (PMID 34315512, 2021). "Noncoding RNAs, including miRNA and lncRNA, are involved in tumor progression by regulating METTL3." (PMID 33879256, 2021). "We showed that METTL3 depletion reduced tumour size, volume and weight." (PMID 34155197, 2021). "Interestingly, a recent study showed that METTL3 recruits YTHDF2 to degrade the m6A-modified transcripts of the tumor suppressors including SETD7 and KLF4, contributing to the progression of bladder cancer." (PMID 33611339, 2021). "Functional inhibition of METTL3 was found to restore chemosensitivity of tumor cells in vitro, implying that inhibition of METTL3 might have potential value in vivo." (PMID 33879256, 2021). "The differential expression of METTL3 among tumors plays a dual role, which may reflect differences in targeting pathways and tumor heterogeneity." (PMID 34858499, 2021). "In addition, METTL3 was involved in m6A-regulated glycolysis, which was one of the critical hallmarks of tumor growth." (PMID 33879256, 2021). "On the other hand, METTL3 can suppress tumor progression under certain conditions." (PMID 33879256, 2021). "We showed that METTL3 depletion reduced tumour size, volume and weight, as well as the amount of lactate in the tumour tissue were restored by APC depletion." (PMID 34155197, 2021). "In addition, depletion of METTL3 disrupted the proliferation and immortality of tumor cells by inhibiting GLI1 in the sonic hedgehog (SHH) pathway." (PMID 33879256, 2021). "In contrast, strong METTL3 staining was observed in ESCC tumor tissues." (PMID 34094960, 2021). "How METTL3 expression compares with CA-125 concentration, which is currently the tumour marker widely used for early detection and prognosis prediction for OC patients, is still unknown." (PMID 34895230, 2021). "METTL3 acts as an oncogene in PCa by promoting the pathogenesis and metastasis of tumor." (PMID 33879256, 2021). "m6A RNA modification may also contribute to T cell-mediated tumor immunity as METTL3 has been reported to regulate T cell homeostasis and differentiation in knockout animal models." (PMID 33814008, 2021). "Interestingly some reseachers believed that m6A writers, such as Mettl3, WTAP, is positively associated with CRC cells invasion, migration, progression, and tumor stem cells with stemness and drug resistance." (PMID 35069586, 2021). "In a mouse model, deletion of METTL3 promoted apoptosis in transplanted tumor cells." (PMID 34660577, 2021). "METTL3 overexpressed cells, miRNA221/222 promotes tumor proliferation by regulating PTEN." (PMID 35004679, 2021). "The importance of METTL3 in tumor progression has been broadly identified in human cancer." (PMID 33879256, 2021). "Methyltransferase-like 3 (METTL3) is an m6A methyltransferase which may function as an oncogenic factor or a tumor suppressor in various types of cancer." (PMID 34842045, 2021). "Moreover, we also found that the knockdown of USP4 effectively alleviated METTL3 decifiency-induced suppressed xenograft tumor formation." (PMID 34335955, 2021). "METTL3 inhibition suppressed tumor growth and lung metastasis in vivo." (PMID 34666602, 2021). "Additionally, stable knockdown of METTL3 effectively suppressed tumor growth as reflected by the significant reduction of tumor size when compared with the shRNA control." (PMID 34631715, 2021).
tumor (continued). "Together, these data suggest that METTL3 may act as a pro-tumor gene involved in DLBCL pathogenesis through regulating m6A methylation." (PMID 33061938, 2020). "METTL3 plays both oncogenic and tumor-suppressive roles in human cancers." (PMID 32854717, 2020). "METTL3 is highly expressed in tumor tissues, while METTL14 expression is low." (PMID 32258108, 2020). "The tumor inhibition rate of everolimus in METTL3-high tumors was significantly higher than that in control tumors (89.92% vs. 73.26%, P = 0.0465), suggesting that METTL3-high tumors could be inhibited by everolimus more effectively." (PMID 33037176, 2020). "Interestingly, in patients with advanced-disease stages (II–IV), METTL3 in tumour cells was an independent factor for DFS (HR = 6.725, P = 0.010) and OS (HR = 5.140, P = 0.021), while CD33+ MDSC density was an independent factor for OS (HR = 8.802, P = 0.037)." (PMID 33059689, 2020). "Furthermore, the expression upregulation after METTL3 knockdown was obviously higher in tumor cell lines than in HEK293T." (PMID 32863943, 2020). "We found that up‐regulated METTL3 increased the proliferation of RB tumour cells." (PMID 33090698, 2020). "We next hypothesized that those CRC patients, harboring higher METTL3 expression, will be more sensitive to the anti-tumor drug candidates targeting METTL3." (PMID 32245489, 2020). "Given the inconsistent role of METTL3 and FTO in tumour progression, it is presumed that the discrepancy may be due to METTL3 and FTO acting on different downstream targets." (PMID 33029866, 2020). "Overexpression of METTL3 or METTL14 also promotes tumor progression in solid cancers." (PMID 32296573, 2020). "In vivo xenograft mice assay was performed and results demonstrated that METTL3 knockdown could inhibit the tumor growth." (PMID 33099572, 2020). "METTL3 was mainly distributed in the nucleus of tumor cells." (PMID 33037176, 2020). "In addition, we analysed the relationship between METTL3 expression in tumour cells and in tumour-infiltrating immune cells and the number of CD33+ MDSCs via Spearman’s correlation coefficient and linear regression." (PMID 33059689, 2020). "Cox model analysis revealed that the level of METTL3 in tumour cells was an independent factor for patient survival, specifically for DFS (HR = 3.157, P = 0.022) and OS (HR = 3.271, P = 0.012), while the CD33+ MDSC number was an independent predictor for DFS (HR: 3.958, P = 0.031)." (PMID 33059689, 2020). "We observed xenograft growth for 3 weeks and found that METTL3 silencing could suppress tumor growth in vivo." (PMID 32175271, 2020). "To determine whether METTL3 affects the growth of RB cells in vivo, we established a subcutaneous tumour model by injecting METTL3‐down‐regulated Y79 cells and control cells (shNC, shRNA1 and shRNA2) into nude mice." (PMID 33090698, 2020). "Importantly, METTL3 expression was positively related to the density of CD33+ cells in tumour tissues (P = 0.011)." (PMID 33059689, 2020). "However, another study showed that METTL3 was a tumor suppressor that inhibited CRC cell proliferation." (PMID 32429972, 2020). "Furthermore, METTL3 accelerates pri-miR221/222 maturation in an m6A-dependent manner, thus promoting tumor proliferation in bladder cancer." (PMID 32296573, 2020). "In conclusion, knocking down METTL3 dramatically inhibited the tumor growth and metastasis in vivo." (PMID 33121495, 2020). "The elevated METTL3 level was correlated with tumor survival and recurrence of GC patients." (PMID 32854717, 2020). "Tumor growth and weight were reduced in the Mettl3-KR cells group." (PMID 32483411, 2020). "It is worth noting that the expressions of METTL14 and METTL3 in tumor tissues are opposite." (PMID 32258108, 2020). "In subcutaneous implantation experiment, METTL3 knockdown could inhibit CRC tumour size and weight in mice." (PMID 32039568, 2020).
tumor (continued). "Instead, a low expression level of METTL3 was detected in certain tumors in which upregulated expression of METTL3 could effectively inhibit the tumor development." (PMID 33061938, 2020). "In addition, in the tumor size ≤5 cm group and grade III group, high METTL3 expression was associated with worse OS and DFS." (PMID 32175271, 2020). "Moreover, the tumour metastasis related genes whose levels were substantially affected by SETD7 were consistent with the roles of METTL3 and YTHDF2 in EMT progression." (PMID 32126149, 2020). "In addition, we found that high levels of METTL3 in tumour cells (HR: 5.502, P = 0.001) and in tumour-infiltrating immune cells (HR: 6.021, P = 0.001) and a high density of CD33+ MDSCs (HR: 5.755, P = 0.001) were associated with decreased OS." (PMID 33059689, 2020). "The level of METTL3 in tumour microenvironments was significantly related to advanced tumour stage." (PMID 33059689, 2020). "Our study demonstrated a comprehensive result of the relationship between METTL3 and CD33 in CC and revealed that METTL3 could induce direct MDSC and tumour-associated MDSC differentiation in vitro." (PMID 33059689, 2020). "METTL3 expression was correlated with tumor size and histological differentiation (p < 0.05)." (PMID 32626532, 2020). "METTL3, a major catalytic enzyme of the m6A methyltransferase complex, plays a dual role (tumour suppressor or oncogene) in multiple human cancers, and regulates tumour cell proliferation, tumour formation migration, invasion and drug resistance." (PMID 32961012, 2020). "Notably, overexpression of FOXO3 in the METTL3‐knockdown Hepa1‐6 cells rescued the sorafenib sensitivity effect, as reflected by the significant decrease of tumor size and tumor weight comparing to the groups treated with solvents." (PMID 32368828, 2020). "METTL3 is one of the most important m6A methyltransferases, and its abnormal expression can change the fate of m6A transcripts, thereby affecting the proliferation, differentiation, and metastasis of various tumor cells." (PMID 32596151, 2020). "METTL3 is known to promote translation in human tumour cells." (PMID 32857912, 2020). "As expected, the METTL3 level was higher in tumor tissues than in the adjacent normal tissues." (PMID 31492150, 2019). "In conclusion, miR-33a exerted tumor-suppressive effects by targeting METTL3 in NSCLC cells." (PMID 31757221, 2019). "In addition, METTL3 can promote tumor progression by regulating oncogene translation independently of m6A reader proteins and its MTase activity." (PMID 31921660, 2019). "The contradictory expression patterns and functions of METTL3 may be largely attributed to differences in the tumor tissue origin, extracellular microenvironment, upstream and downstream regulatory factors, and research methods." (PMID 31921660, 2019). "In addition, the methylation levels within the METTL3 CpG island in non-tumor pancreatic tissues were significantly lower in smokers than in nonsmokers." (PMID 31015415, 2019). "The tumor suppressor role of METTL3 in this research was related to the P38/ERK pathway." (PMID 31921660, 2019). "And METTL3/miR-1246/SPRED2 axis played an important role in tumor metastasis." (PMID 31492150, 2019). "Additionally, various studies in different cancer systems supported that METTL3 and m6A modification are involved in the transformation and tumor progression." (PMID 30781903, 2019). "From the in vivo experiment, we observed that stable knockdown of METTL3 can cause significant reduction in tumor size and weight with respect to the nontarget shRNA control." (PMID 31870368, 2019). "Negative METTL3 expression was significantly associated with larger tumor sizes and higher histological grade." (PMID 31921660, 2019). "In addition, SOX2 overexpression subsequently increased the tumor incidence and the frequency of tumorigenic cells among both control and METTL3 knockdown SW620 cells." (PMID 31230592, 2019).
tumor (continued). "Furthermore, IHC results showed that the expression of METTL3 in tumor tissues was dramatically elevated compared to that in normal tissues." (PMID 31492150, 2019). "Moreover, the tumors injected with METTL3 overexpression (oeMETTL3) cells grew more rapidly than those injected with control cells (oeNC) in subcutaneous xenograft tumor model." (PMID 31228940, 2019). "HBXIP enhances the expression of METTL3 by suppressing the tumor suppressor let-7g." (PMID 30062093, 2018). "For instance, in TGCTs, higher VIRMA expression was found to be associated with low disease stage; in addition, in KCa, RBM15B overexpression (an eraser) associated with advanced disease at diagnosis, whereas the writer METTL3 was reported to act as a tumor suppressor." (PMID 30428628, 2018). "SOCS2, a known tumor suppressor, was identified to be a downstream target of METTL3." (PMID 30149601, 2018). "Besides, in terms of phenotypes, knockdown of METTL3 promoted GSCs growth and self‐renewal as well as tumour progression, and vice versa." (PMID 30039919, 2018). "Additionally, depletion of METTL3 or METTL14 enhances tumor tumorigenicity while FTO inhibitor treatment prevents tumor deterioration." (PMID 30062093, 2018). "And SOCS2 mRNA is a downstream target of METTL3 and a tumor inhibitor in HCC." (PMID 30062093, 2018). "Clinicopathological factors were compared between these two groups, demonstrating that negative METTL3 expression was associated with larger tumor size (P=0.010) and higher histological grade (P=0.021)." (PMID 29221190, 2017). "Moreover, multivariate analysis indicated that age (P=0.001), histological grade (P=0.011), tumor stage (P=0.000) and METTL3 expression (P=0.026) were independent prognostic indexes for survival." (PMID 29221190, 2017). "Overall, METTL3 might act as a tumor suppressor in the development, biological progress and survival of RCC patients." (PMID 29221190, 2017). "Negative METTL3 expression was associated with larger tumor size (P=0.010) and higher histological grade (P=0.021)." (PMID 29221190, 2017). "The results showed that negative METTL3 expression was associated with larger tumor size and higher histological grade." (PMID 29221190, 2017). "In CD8+ T cells, METTL3 enhances the stability and translational efficiency of genes associated with the T cell receptor (TCR) signaling pathway, thereby promoting their proliferation, activation, and the expression of effector molecules, which ultimately strengthens anti-tumor immunity." (PMID 40678060, 2025). "Therefore, targeting METTL3 may achieve multiple anti-tumor effects and possibly possess favorable tumor specificity." (PMID 40678060, 2025). "The necessity of an m6A mRNA reader for METTL3-mediated regulation remains uncertain, and further research is required to determine whether this process is a normal part of cell development or a response to tumor stress." (PMID 40136363, 2025). "At the age of 9 months, compared with the control mice treated with DEN, DEN‐treated Mettl3 cKO mice displayed increased tumor nodules and aggravated changes in liver gross appearance, alongside increases in liver‐to‐body weight ratio and larger maximum surface tumor size." (PMID 40103332, 2025). "Therefore, targeting METTL3 inhibition could reduce the immunosuppressive function of tumour‐infiltrating myeloid cells, potentially enhancing resistance to cancer therapies." (PMID 41020792, 2025). "In addition, given the increasing focus on miRNAs as therapeutic targets, inhibiting miR-493-5p could offer a strategy to elevate METTL3 levels and restore its tumor-suppressive effects." (PMID 39874138, 2025). "Building upon prior research suggesting that chemokines like C-X-C motif chemokine ligand 9 (CXCL9) and C-X-C motif chemokine ligand 10 (CXCL10) recruit CAR-NK cells, we hypothesized that tumor cell m6A methylation, regulated by Methyltransferase-like 3 (METTL3), influences chemokine secretion." (PMID 39497707, 2025).